LEP (leptin)
Diseases named in the same sentence as LEP in open-access papers (continued):
Sharing a sentence is not in itself a finding about the gene and the disease.
Obesity (continued). "Seven proteins (adipsin, chemerin, leptin, vaspin, apo-B100, apo-C2, apo-C4) showed significantly increased abundance in participants with obesity compared to the normal weight control group, whereas adiponectin and apo-D levels were significantly reduced." (PMID 32054032, 2020). "Another adipokine, adiponectin has been shown to have an opposite effect to leptin in inflammation and insulin resistance, and the ratio of leptin to adiponectin is considered as a marker for developing T2D and obesity." (PMID 33414704, 2020). "The effect of leptin in increasing insulin resistance in women with NWO is similar to patients with obesity." (PMID 33198735, 2020). "Leptin plays a major role in the regulation of energy homeostasis and obesity and is involved in endocrine functions, including the regulation of immune and inflammatory responses, angiogenesis, reproduction, and bone formation." (PMID 33584788, 2020). "Leptin has been proposed to be at least one molecular mechanism involved in dysfunctional B cell function in individuals with obesity." (PMID 32983154, 2020). "In this paper, we introduce an electrochemical biosensor that adopts o-Phenylenediamine (oPD) on screen-printed gold electrodes (SPGEs) for detecting the leptin from a mouse model of diet-induced obesity (DIO)." (PMID 33374256, 2020). "The deletion, the knockdown or the pharmacological inhibition of TLR4 protects mice from obesity, inflammation, and leptin resistance." (PMID 32576879, 2020). "As leptin reduces appetite and body weight, the paradoxical coexistence of obesity and hyperleptinemia suggests the pathology of “leptin resistance”." (PMID 33489589, 2020). "The use of mice models lacking LepR in SF1 neurons has demonstrated that these neurons mediate, at least in part, the anti-obesity effect of leptin." (PMID 32069871, 2020). "Insulin and leptin resistance are hallmarks of obesity, occurring following overnutrition and before the onset of major weight gain, and both are associated with mitochondrial dysfunction in the brain." (PMID 33240218, 2020). "Leptin, which is secreted by adipocytes and significantly enhanced in obesity, has been shown to promote CSCs, potentially through regulation of Notch signaling." (PMID 32098183, 2020). "Collectively, our results unveil an unrecognized leptin/Sh2b1/sympathetic nerve/adipose thermogenesis axis that combats obesity, type 2 diabetes, and liver steatosis." (PMID 32251290, 2020). "The current cross-sectional study is aimed to evaluate the metabolite profile of diet-induced obesity in a porcine model of leptin resistance." (PMID 32150837, 2020). "We found a parallel but opposite behavior of SIRT1, leptin and adiponectin in patients with obesity." (PMID 33202604, 2020). "Unfortunately, recent data have shown, that most cases of obesity are characterized by excessive leptin production and leptin resistance." (PMID 33322719, 2020). "In animal models, high sodium intake increases endogenous production of fructose, thereby triggering the processes of leptin resistance and hyperphagia, which result in obesity, insulin resistance and hepatic steatosis among mice." (PMID 32130310, 2020). "Leptin is produced by adipocytes in proportion to adipose tissue mass and is therefore increased in obesity." (PMID 33584724, 2020). "Leptin levels are highly upregulated in obesity, but obese individuals become “leptin resistant” by losing their ability to control food ingestion, despite the presence of high levels of leptin." (PMID 32471061, 2020). "Future research is required to understand the precise role of leptin directly in different cardiac cell types (e.g., cardiomyocytes, endothelial cells or fibroblasts), which may open up new avenues for the treatment of obesity- and diabetes-associated cardiomyopathy." (PMID 32655492, 2020).
Obesity (continued). "In summary, we demonstrated that administration of the gut microbe L. fermentum LM1016 ameliorated diet-induced obesity and improved metabolic biomarkers, including glucose, insulin, and leptin." (PMID 32917958, 2020). "Our present study was designed to assess the potential role of irisin, adiponectin, leptin and gene polymorphism of PNPLA3, leptin and adiponectin as predictive markers of diabetes associated with obesity." (PMID 32544194, 2020). "Alteration of leptin, obesity-correlated hormones, dietary intervention and bariatric surgery all attenuate symptomatic obesity through lowering these pro-inflammatory cytokines in circulation." (PMID 32429195, 2020). "Although elevated leptin concentrations reflect excess energy availability and the need to reduce energy intake, a state of relative leptin resistance arises in obesity." (PMID 32407841, 2020). "Other bioactive food compounds have also been proven to be able to reduce circulating leptin levels in obesity." (PMID 32630697, 2020). "They reported an odds ratio of 1.7 of being overweight in both males and females using anti-H1 compared to controls (95% CI, 1.23–2.31), thought to be due to the disruption of insulin and leptin signaling, leading to obesity." (PMID 33348647, 2020). "Paradoxically, in common forms of obesity, paradoxically, as fat mass increase, circulating leptin concentrations also increase but fail to suppress food intake." (PMID 32545900, 2020). "Re-expression of LepRb in the brain reverses obesity and its related metabolic disorders in LepRb null mutant mice, suggesting the metabolic actions of leptin are largely mediated by the central nervous system." (PMID 33071984, 2020). "Most people with obesity have very high levels of leptin in their blood, but are resistant to its effects and will therefore continue to feel hungry despite having stored enough energy." (PMID 33210603, 2020). "Obesity is also marked with high concentrations of leptin, which is also known to trigger the production of IL-6 and TNF-α from adipose tissues and to increase the risk for viral infection." (PMID 32650509, 2020). "Several studies have described reductions in leptin and increases in adiponectin in adults with severe obesity undergoing bariatric surgery." (PMID 33004989, 2020). "Intriguingly, mTOR is also one of the signal mediators of obesity related factors, such as leptin, adiponectin, and inflammatory cytokines, through the Akt/PI3K or AMPK pathways." (PMID 33304380, 2020). "These new findings, in conjunction with prior studies demonstrating that leptin drives obesity-mediated breast tumor progression, provided rationale for analyzing the relationship between FGFR1 mRNA and the leptin receptor (LepR) mRNA in breast cancer." (PMID 33019728, 2020). "Leptin levels, on the other hand, are elevated in obesity and are positively correlated with levels of inflammatory cytokines, namely IL1 beta, IL6 and IL12 amongst others." (PMID 32069845, 2020). "Obesity activates the sympathetic nervous system, which can lead to hypertension, in part due to the central actions of adipose-derived leptin." (PMID 32538782, 2020). "Adipose tissues including white adipose tissue (WAT) are important for metabolism and hormones derived from WAT such as leptin and adiponectin are involved in regulating obesity and diabetes." (PMID 33414704, 2020). "Their analysis also identified four obesity-associated genes (CPE, LEP, NPY1R, and NPY5R) that were positively correlated with weight gain and two genes (APOM and CRP) that were negatively correlated with weight gain." (PMID 32151267, 2020). "Higher leptin levels are positively correlated with obesity and cardiovascular disease (Ekmen, Helvaci, Gunaldi, Sasani, & Yildirmak, 2016)." (PMID 32762010, 2020). "Previous studies demonstrated that structural alterations of the MC4R receptor and the insufficient number of MC3R receptors in mice models can result in leptin resistance and obesity." (PMID 32033608, 2020).
Obesity (continued). "Obesity is well-known to be associated with elevated circulating levels of insulin, insulin-like growth factor 1 (IGF-1), leptin, and inflammation." (PMID 32454823, 2020). "Both angiotensin II and the leptin from the adipocytes can potentiate sympathetic activity and act synergistically to promote obesity-related hypertension." (PMID 32403968, 2020). "The phenomenon of high serum leptin levels coexisting with obesity and abnormal glycolipid metabolism is leptin resistance, and leptin resistance is also observed in obese people." (PMID 32920548, 2020). "It is known that anti-obesity hormone leptin signaling as well as insulin signaling mediate the regulation of PPARα." (PMID 31963301, 2020). "In obesity, circulating leptin levels are increased, as is its mRNA expression in adipocytes in obese patients." (PMID 33081064, 2020). "Obesity indices such as waist circumference and percent body fat correlated significantly positively with serum leptin level." (PMID 31690939, 2020). "This study was performed to evaluate anti-obesity potential of Commiphora myrrha resin ethanolic extract (CME) with the respect to expression of leptin, adiponectin and uncoupling protein 1 (UCP1) in rats." (PMID 32197395, 2020). "At the onset of obesity, the excessive levels of these two hormones lead to the impairment of their functions in target tissues, resulting in insulin/leptin resistance." (PMID 33218042, 2020). "A new molecular link between obesity, chronic inflammation and periodontal diseasehas been investigated: leptin." (PMID 32667531, 2020). "Attempts to use leptin by itself as an obesity treatment have been disregarded on account of the leptin resistance found in obese patients." (PMID 32069871, 2020). "Leptin, produced mainly by adipocytes, has been proposed as a mediator between obesity, inflammation, and breast cancer development." (PMID 32736587, 2020). "Serum LEP concentration is considered a reliable marker of adiposity in dogs regardless of age, gender and breed variations, and decreases with weight loss, and thereby it could be a potentially useful tool to assess the obesity status also in the clinical setting." (PMID 33316917, 2020). "Neonatal administration of MSG in rodents was previously demonstrated to affect the arcuate nucleus and the ventromedial nucleus of hypothalamus and to impair leptin signaling, resulting in obesity in rodents that were fed a conventional diet." (PMID 32103741, 2020). "Physicians should be encouraged to include leptin levels in the management of obesity and other metabolic syndromes." (PMID 33489589, 2020). "The present data indicate that circulating leptin levels are significantly increased in climacteric women, even in the absence of a significantly increased BMI or other indicators of obesity or metabolic dysfunction." (PMID 32555994, 2020). "Decreased expression of kisspeptin in the ARC was observed in female mice that are centrally resistant to leptin signaling and prone to obesity-induced infertility." (PMID 33088334, 2020). "In human studies, middle-aged men with high blood leptin tended to develop obesity, as well as a high blood pressure." (PMID 33114326, 2020). "We have also confirmed that biological markers of obesity correlate with BMI, ghrelin and adiponectin negatively and leptin positively." (PMID 32085704, 2020). "In summary, considerable evidence implicates a role for leptin in obesity-induced sympathoexcitation in males." (PMID 32160920, 2020). "In animal models, it had also been demonstrated that a high-salt diet can lead to endogenous fructose production, leptin resistance and excessive appetite, and can lead to obesity, insulin resistance and fatty liver." (PMID 32411541, 2020). "Although miR181b-5p and miR219-5p are known to regulate glucose homeostasis and obesity respectively, our study is the first to address how elafin-dependent miR181b-5p and miR219-5p regulate adipose leptin expression." (PMID 32733043, 2020).
Obesity (continued). "A more recent study on Saudi women with high body mass index (BMI), waist circumference, and metabolic syndrome confirmed a significant correlation between leptin levels and obesity." (PMID 33192583, 2020). "In contrast to leptin, the baseline ghrelin rhythm was lower in the obesity group than in the control group." (PMID 32230732, 2020). "Regarding adipokines, as expected, the adiponectin level was lower (p < 0.001), while the leptin level was higher (p < 0.001) in patients with obesity compared with controls." (PMID 32316563, 2020). "Leptin and adiponectin are adipokines secreted by white adipose tissue and are known to be related to obesity and involved in glucose and lipid metabolism." (PMID 32164209, 2020). "At baseline, the leptin mesor was significantly higher in the obesity group subjects than in the control subjects." (PMID 32230732, 2020). "Here, we identify a role for the obesity-cytokine leptin in sustaining aromatase inhibitor (AI) resistant growth and progression in breast cancer." (PMID 32260113, 2020). "Third, we assumed that the endocrine profile of participants with obesity is characterized by high insulin resistance, high leptin levels, elevated AG/UAG ratio, and low total ghrelin levels." (PMID 32721994, 2020). "Knock-in mice carrying a loss-of-function variant (NCOA1L1376P) identified in human obese patients show lower POMC gene expression, impaired leptin-induced depolarization of POMC neurons, increased food intake, and increased susceptibility to obesity." (PMID 32449767, 2020). "Due to its anti-obesogenic effect affecting both food intake and energy expenditure, leptin is one of the principal druggable targets to fight obesity and its comorbidities." (PMID 32069871, 2020). "SOCS3-specific knockout mice have shown improved diet-induced obesity, leptin, and insulin resistance compared with wild-type mice." (PMID 32168898, 2020). "In a course of obesity, an increased serum level of leptin coexists with tissue receptor resistance." (PMID 33008429, 2020). "Potential physiological consequences of such a mechanism are that in pathological situations, the annulling effect of RSTN on leptin signaling favors the development of hyperinsulinemia to overcome insulin resistance during obesity." (PMID 32545900, 2020). "This retrospective study concludes that anti-obesity hormone namely, leptin spikes up in patients with the first occurrence of myocardial infarction which can be due to target organ resistance to leptin in such patients." (PMID 33489600, 2020). "Obesity and inflammation expand and mobilize MDSCs and their precursors via molecules such as IL-6, CRP, IL-1β, and leptin, increasing their susceptibility to tumor-derived signals that further drive their recruitment and suppressive capacity." (PMID 33123173, 2020). "For the monogenetic obesity, several of the genes are involved in the leptin–melanocortin pathway, mainly regulated in the hypothalamus." (PMID 32982666, 2020). "In this sense, either as an independent factor or by mediating estrogens action, leptin has been proposed as a key link between obesity and different types of cancer." (PMID 32824322, 2020). "It has been seen that adiponectin levels are lowered and leptin levels are elevated in those with obesity." (PMID 32397260, 2020). "Leptin is a satiety hormone that regulates energy balance as a long-term regulator suppressing food intake preventing obesity." (PMID 33603741, 2020). "The obtained results indicate the potential of the sheep model in studies on leptin resistance in the course of obesity." (PMID 32532062, 2020). "Our results showed that the administration of scopolin decreased serum levels of insulin and leptin, indicating the inhibition of OVX-induced obesity by preventing insulin/leptin resistance." (PMID 33218042, 2020). "A leptin-resistant mouse model (Lepr db/db) developed obesity and diabetic phenotypes showing high levels of TAU protein phosphorylation." (PMID 32982666, 2020).
Obesity (continued). "Macrophages are key regulators of adipose tissue inflammation in obesity and, therefore, the effects of leptin on macrophages is highly relevant in the setting of diet-induced obesity." (PMID 33584724, 2020). "Leptin levels are decreased during fasting and are increased after feeding to inhibit appetite, making it an anti-obesity hormone." (PMID 33489600, 2020). "Exposure to chronically elevated levels of leptin in the context of obesity led to the development of an exhausted phenotype in T-cells, concomitant with an increased expression of PD-1." (PMID 33604295, 2020). "Obesity is characterized by changes in adipokine secretion, including an increase in leptin, a 16-kDa peptide hormone, which is predominantly produced by the white adipose tissue." (PMID 32709161, 2020). "In a genetic obesity animal model with leptin deficits, for example, synaptic plasticity was shown to be impaired in the hippocampus." (PMID 32987813, 2020). "Our data indicates that in utero environmental factors affected by maternal diet program alterations in the set point around which leptin regulates body weight in offspring into adulthood contributing to obesity." (PMID 32407841, 2020). "The ob/ob mice, due to insufficient plasma leptin levels, display a phenotype of hyperphagia and extreme obesity accompanied by hyperglycemia and hyperinsulinemia." (PMID 32832353, 2020). "Overnutrition impairs mTORC1 activity and decreases mTORC1 signaling in rat hypothalamus, which is implicated to assist in the development of hyperphagia, weight gain, and leptin resistance in HFD-induced obesity." (PMID 33532487, 2020). "The downregulation of stearoyl-coenzyme A desaturase-1 (SCD1), and the enhancement of insulin and leptin sensitivity have been suggested as a curative measures in HFD-induced obesity." (PMID 32260306, 2020). "In obesity, leptin levels are elevated and oscillate around a higher level of body weight, and the failure to suppress appetite is consistent with a state of leptin resistance." (PMID 32407841, 2020). "The origin of leptin resistance is still not fully understood, and solving this puzzle is widely considered the key to both understanding how obesity develops and identifying effective therapeutic interventions." (PMID 32545900, 2020). "In contrast, the induction of Xbp1s in POMC neurons protects against diet-induced obesity and improves leptin and insulin sensitivity." (PMID 32313051, 2020). "Serum leptin concentrations are increased in patients with obesity, type 2 diabetes, metabolic syndrome, and cardiovascular disease, whereas serum adiponectin concentrations are decreased in these disorders." (PMID 32985609, 2020). "The hyperleptinemia and leptin resistance, a common scenario on obesity, leads to a reduction in adipose tissue-infiltrating regulatory T cells (Treg), amplifying local inflammation." (PMID 32028959, 2020). "Leptin and resistin present a similar behavior and can be found in high levels in conditions such as obesity and breast cancer." (PMID 32903534, 2020). "Insulin resistance is improved by 4-HNE, which also selectively inhibits leptin signaling, possibly promoting the pathogenesis of leptin resistance in obesity." (PMID 31963301, 2020). "Correlation between adipose tissue, indirect obesity, and vascularization has been found before for leptin, which is known for in vitro stimulation of angiogenesis in goat luteal cells." (PMID 32957618, 2020). "The role of leptin in the development, pathophysiology, acceleration or complications of many diseases as a consequence of obesity seems clear." (PMID 32824322, 2020). "Leptin levels are increased in obesity and elevated leptin levels deteriorate lung and cardiovascular function." (PMID 33123087, 2020). "In fact, IL1R1 has been identified as a mediator that increases leptin sensitization secondary to the action of celastrol, an effective drug treatment of obesity." (PMID 32824322, 2020).